LINC03033 (long independently transcribed non-coding RNA 3033)
Synonyms: LncRNA-CAF; FLJ22447
Gene: Long non-coding RNA gene on chromosome 14 (61,570,405 to 61,658,696, forward strand). Ensembl gene ENSG00000232774.
Diseases named in the same sentence as LINC03033 in open-access papers:
LINC03033 is named in the same sentence as 2 diseases in open-access papers, as found by Europe PMC text mining. Sharing a sentence is not in itself a finding about the gene and the disease.
LINC03033 shares sentences with these, for which no sentence is quoted: gastric adenocarcinoma (1 paper); metastatic tumor (1).